MRPL47 (mitochondrial ribosomal protein L47)
Synonyms: L47mt; MRP-L47; NCM1; CGI-204; uL29m
Tractability: Small molecule: a structure with a bound ligand is known. PROTAC: ubiquitination databases record sites on it; its protein half-life has been measured.
Gene: Protein-coding gene on chromosome 3 (179,582,420 to 179,604,659, reverse strand). Ensembl gene ENSG00000136522.
Subcellular location: Mitochondrion
Subcellular location (Human Protein Atlas): Mitochondria
Pathways (Reactome):
Metabolism of proteins: Mitochondrial ribosome-associated quality control; Mitochondrial translation elongation; Mitochondrial translation initiation; Mitochondrial translation termination
Gene Ontology:
Molecular function: structural constituent of ribosome
Biological process: mitochondrial translation; translation
Cellular component: mitochondrial large ribosomal subunit; mitochondrion; mitochondrial inner membrane; mitochondrial ribosome
Genetic constraint (gnomAD): Loss-of-function variants: 19 observed, 18.41 expected, observed/expected ratio (o/e) 1.03, 90% interval 0.72 to 1.51. The upper end of that interval is the gene's LOEUF score, 1.51, which puts it in group 6 of 6, group 1 being the genes least tolerant of losing a copy. Missense variants: 200 observed, 171.97 expected, observed/expected ratio (o/e) 1.16, 90% interval 1.04 to 1.31. Synonymous variants: 70 observed, 62.34 expected, observed/expected ratio (o/e) 1.12, 90% interval 0.93 to 1.37.
Homologues: Orthologues: chimpanzee MRPL47 (99% identical), macaque MRPL47 (98% identical), pig MRPL47 (83% identical), dog MRPL47 (81% identical), mouse Mrpl47 (78% identical), rat Mrpl47 (77% identical), rabbit MRPL47 (76% identical), tropical clawed frog mrpl47 (51% identical), zebrafish mrpl47 (50% identical), Drosophila melanogaster mRpL47 (36% identical), Caenorhabditis elegans mrpl-47 (29% identical).
Diseases named in the same sentence as MRPL47 in open-access papers:
MRPL47 is named in the same sentence as 9 diseases in open-access papers, as found by Europe PMC text mining. Sharing a sentence is not in itself a finding about the gene and the disease. The quoted sentences say what the papers report.
acute lymphoblastic leukemia (2 papers, 2022). Leukemia with an acute onset, characterized by the presence of lymphoblasts in the bone marrow and the peripheral blood. "MRPL47 gene mutation is a new high risk factor of vincristine induced peripheral neuropathy in children with acute lymphoblastic leukemia." (PMID 35449547, 2022). "A variant of MRPL47 is a putative new risk factor for vincristine-induced peripheral neuropathy in childhood acute lymphoblastic leukemia." (PMID 35979430, 2022).
lung carcinoma (2 papers, 2020 to 2025). "Consistent with this, we showed that copy number amplification drives MRPL47 overexpression in lung cancer, with amplified samples exhibiting significantly elevated MRPL47 expression compared to normal and diploid samples (p-value< 0.0001)." (PMID 41407038, 2025). "Furthermore, analysis using the Lung Cancer Explorer database confirmed significantly elevated MRPL47 expression in NSCLC compared to normal lung tissues." (PMID 41407038, 2025).
lung adenocarcinoma (1 paper, 2025). A carcinoma that arises from the lung and is characterized by the presence of malignant glandular epithelial cells. "Silencing of MRPL47 in lung adenocarcinoma (LUAD) cells inhibited proliferation, growth, and migration, highlighting its potential as a therapeutic target." (PMID 41407038, 2025).
cancer (3 papers, 2020 to 2025). A tumor composed of atypical neoplastic, often pleomorphic cells that invade other tissues. "This study explores the role of MRPL47 in cancer cells, emphasizing its influence on mitochondrial function and tumor progression." (PMID 41407038, 2025). "Knockdown of MRPL47 using shRNA significantly impaired cancer cell proliferation, migration, and colony formation." (PMID 41407038, 2025). "The therapeutic significance of MRPL47 was highlighted by its amplification and overexpression in several cancer types, especially NSCLC." (PMID 41407038, 2025). "Extending our analysis, we examined MRPL47 expression and amplification across a panel of other cancer types, finding consistent amplification and overexpression in all types investigated." (PMID 41407038, 2025). "In conclusion, MRPL47 is essential for cancer cell growth and proliferation through its role in mitochondrial function." (PMID 41407038, 2025). "In vivo investigations are crucial to confirm the therapeutic efficacy of targeting MRPL47 in cancer models." (PMID 41407038, 2025). "Our findings elucidate the molecular factors influencing the dependency of cancer cells on MRPL47." (PMID 41407038, 2025). "Notably, MRPL47 expression demonstrated prognostic significance, predicting poor survival in various other cancer types as well." (PMID 41407038, 2025). "However, the roles of NCBP2, MKRN3, and MRPL47 in cancers are still unclear." (PMID 33505420, 2020).
tumor (1 paper, 2025). "Consistent with the tumor volume measurements, the endpoint tumor weights in the MRPL47 knockdown group were significantly lower compared to the control group (p < 0.01)." (PMID 41407038, 2025). "By the endpoint of the experiment (day 17), the mean tumor volume in the MRPL47 knockdown group was ∼60% lower than that of the control group, demonstrating the critical role of MRPL47 in sustaining tumor growth in vivo." (PMID 41407038, 2025). "We observed a significant reduction in tumor growth in the MRPL47 knockdown group compared to the control group." (PMID 41407038, 2025). "Our study delineates the crucial role of MRPL47 in NSCLC tumor progression by regulating mitochondrial function." (PMID 41407038, 2025). "Collectively, these findings position MRPL47 as a critical regulator of mitochondrial dynamics and ROS balance in tumor progression, suggesting new therapeutic strategies targeting this pathway." (PMID 41407038, 2025). "At the protein level, data from the clinical proteomic tumor analysis consortium dataset revealed increased MRPL47 protein abundance in NSCLC samples relative to corresponding normal samples." (PMID 41407038, 2025). "These in vivo findings corroborate our in vitro observations and establish that MRPL47 is essential for tumor growth and progression in a physiologically relevant animal model." (PMID 41407038, 2025). "The tumor volume was markedly decreased in mice bearing MRPL47-depleted H460 cells throughout the observation period." (PMID 41407038, 2025). "Given the relationship between mitochondrial dysfunction and the tumor environment, MRPL47 mediated ROS generation's effect on immune cell recruitment and activation is crucial to investigate." (PMID 41407038, 2025). "Altogether, these findings establish that MRPL47 is amplified and overexpressed in NSCLC, functions as a strong prognostic predictor, and critically promotes tumor progression by modulating mitochondrial function and the ROS-p38-p21-Rb-E2F signaling axis." (PMID 41407038, 2025).
MRPL47 also shares sentences with these, for which no sentence is quoted: peripheral neuropathy (2 papers); non-small cell lung carcinoma (1); ovarian carcinoma (1); Parkinson disease (1).